TAAR6 (trace amine associated receptor 6)
Description:
Olfactory receptor specific for trace amines, such as beta-phenylethylamine (beta-PEA). Trace amine compounds are enriched in animal body fluids and act on trace amine-associated receptors (TAARs) to elicit both intraspecific and interspecific innate behaviors. Beta-PEA-binding causes a conformation change that triggers signaling via G(s)-class of G alpha proteins (GNAL or GNAS).
Synonyms: TaR-6; TaR-4; TA4; TAR4; TRAR4; TAR6
Tractability: Small molecule: it belongs to a druggable protein family. Antibody: UniProt places it where antibodies can reach, with high confidence; its Gene Ontology location is reachable by antibodies, with high confidence; UniProt predicts a signal peptide or a membrane-spanning region.
Target class: Monoamine receptor; Trace amine receptor; Membrane receptor; Family A G protein-coupled receptor; Small molecule receptor (family A GPCR)
Gene: Protein-coding gene on chromosome 6 (132,570,322 to 132,571,359, forward strand). Ensembl gene ENSG00000146383.
Subcellular location: Cell membrane
Pathways (Reactome):
Signal Transduction: Amine ligand-binding receptors; G alpha (s) signalling events
Gene Ontology:
Molecular function: G protein-coupled receptor activity; trace-amine receptor activity
Biological process: adenylate cyclase-activating G protein-coupled receptor signaling pathway; G protein-coupled receptor signaling pathway; sensory perception of smell
Cellular component: plasma membrane; membrane
Genetic constraint (gnomAD): Loss-of-function variants: 15 observed, 18.78 expected, observed/expected ratio (o/e) 0.8, 90% interval 0.53 to 1.23. The upper end of that interval is the gene's LOEUF score, 1.23, which puts it in group 5 of 6, group 1 being the genes least tolerant of losing a copy. Missense variants: 501 observed, 440.07 expected, observed/expected ratio (o/e) 1.14, 90% interval 1.06 to 1.23. Synonymous variants: 192 observed, 173.09 expected, observed/expected ratio (o/e) 1.11, 90% interval 0.99 to 1.25.
Homologues: Orthologues: chimpanzee TAAR6 (98% identical), rabbit TAAR6 (86% identical). Paralogues in human: TAAR8 (79% identical), TAAR9 (69% identical), TAAR5 (41% identical), TAAR1 (39% identical), TAAR2 (36% identical), HRH2 (29% identical), HTR1A (28% identical), HTR1D (28% identical), HRH1 (26% identical), HRH3 (26% identical), HTR4 (26% identical), DRD1 (26% identical), and 13 more.
Diseases named in the same sentence as TAAR6 in open-access papers:
TAAR6 is named in the same sentence as 16 diseases in open-access papers, as found by Europe PMC text mining. Sharing a sentence is not in itself a finding about the gene and the disease. The quoted sentences say what the papers report.
schizophrenia (4 papers, 2009 to 2022). A major psychotic disorder characterized by abnormalities in the perception or expression of reality. "Taar6 was reported to be associated with schizophrenia in an ethnical heterogenous sample of 192 families, previously linked to 6q23." (PMID 31643000, 2020). "Although the current views on TAAR6 expression in the brain remain controversial, several TAAR6 gene polymorphisms have been associated with mental diseases, including schizophrenia and bipolar affective disorder, which indirectly indicates the involvement of TAAR6 in brain functioning." (PMID 36139098, 2022). "TAAR6 was originally identified in families with schizophrenia." (PMID 19445674, 2009).
autism spectrum disorder (1 paper, 2020). A spectrum of developmental disorders that includes autism, and Asperger syndrome. "Finally, results of transcriptomic and peptidomic analyses, although very preliminary, suggest that TAARs, in particular TAAR6, might be involved in the pathophysiology of autism spectrum disorders and vascular cognitive impairment." (PMID 31643000, 2020).
Cognitive impairment (1 paper, 2020). Abnormal cognition is characterized by deficits in thinking, reasoning, or remembering. "Finally, with the use of transcriptomic and peptidomic techniques, dysregulations of TAARs (especially TAAR6) have been identified in brain disorders characterized by cognitive impairment." (PMID 31643000, 2020).
melanoma (1 paper, 2022). A malignant, usually aggressive tumor composed of atypical, neoplastic melanocytes. "It was found that coexpression of TAARs with genes inquired in neurotransmitter signaling is lost in melanoma, and tumor-specific association of TAAR6 expression with the mTOR pathway and inflammatory signaling is observed." (PMID 35053262, 2022). "Instead, the TAAR6 coexpressed gene cluster in melanoma is enriched in pathways “Inflammatory mediator regulation of TRP channels” representing processes in nociceptive dorsal root ganglion (DRG) neurons, and “mTOR signaling pathway”." (PMID 35053262, 2022). "This analysis revealed the loss of normal TAARs function in melanoma and the potential involvement of TAAR6 in some melanoma-specific processes." (PMID 35053262, 2022). "Differential expression analysis demonstrated the drastic decrease of TAAR1, TAAR2, TAAR5, TAAR6, and TAAR8 expression in melanomas compared to benign nevi with only TAAR6, TAAR8, and TAAR9 remaining detectable in malignant tumors." (PMID 35053262, 2022). "In contrast, TAAR6, TAAR8, and TAAR9 were expressed in 12.7%, 11.3%, and 5.3% of tumor specimens, respectively, so their expression is comparable with DRD2, of which expression and activity are well established in melanoma." (PMID 35053262, 2022). "In this study, TAAR6, TAAR8, and TAAR9 expression was found in melanoma samples." (PMID 35053262, 2022). "However, TAAR6, TAAR8, and TAAR9 were still expressed in melanoma." (PMID 35053262, 2022).
mental disorder (1 paper, 2022). A disease that has its basis in the disruption of mental process. "Thus, expression of TAAR6 in the brain areas involved in mental disorders, such as the prefrontal cortex or nucleus accumbens, was found in this study." (PMID 36139098, 2022).
cancer (3 papers, 2018 to 2023). A tumor composed of atypical neoplastic, often pleomorphic cells that invade other tissues. "Pathway enrichment results did not clearly indicate the nature of the association of TAARs with identified biological processes, and the results were insufficient to determine if TAAR6 was implicated in cancer-associated pathways, or TAAR6 only co-regulates with mTOR signaling in tumors." (PMID 35053262, 2022). "We estimated TAARs’ (including TAAR1, TAAR2, TAAR5, TAAR6, TAAR8, and TAAR9) associations with BC stage, grade, and molecular subtypes in these data and identified that the expression of all TAARs was associated with more unfavorable cancer subtypes, including basal-like and HER2-positive tumors." (PMID 37759760, 2023). "RNAseq data from 12 published cancer studies obtained from cBioPortal detected RNA for TAAR1, TAAR2, TAAR5, TAAR6, TAAR8, and TAAR9 in various cancers." (PMID 29997511, 2018).
tumor (3 papers, 1990 to 2023). "Other TAARs, i.e., TAAR1, TAAR6, and TAAR9, are expressed in the neoplastic epithelium and tumor stroma at the same levels." (PMID 37759760, 2023). "The identified differences in TAAR2 and TAAR5 expression levels between tumor cells and stroma seem to be reproducible in different groups, including inflammatory cancer, whilst tumorous and stromal cells demonstrate similar expression levels of TAAR1, TAAR6, and TAAR8." (PMID 37759760, 2023).
TAAR6 also shares sentences with these, for which no sentence is quoted: Anxiety (1 paper); bipolar affective disorder (1); brain disorder (1); hematologic malignancies (1); lung carcinoma (1); migraine (1); neurodegenerative disease (1); psychiatric disorder (1); squamous cell carcinoma (1).